MMP13 (matrix metallopeptidase 13)
Diseases named in the same sentence as MMP13 in open-access papers (continued):
Sharing a sentence is not in itself a finding about the gene and the disease.
tumor (continued). "Our evidence demonstrates that increased tumor-derived MMP-13 expression independently predicts poor prognoses." (PMID 18373849, 2008). "Mmp13 mRNA was found in carcinoma-associated fibroblasts located in the central areas of the MMTV-PyMT tumors, where tumor dedifferentiation and invasion is prominent." (PMID 18698413, 2008). "In this study, we found MMP-13 protein in the cytoplasm of both cancer cells and tumor-adjacent fibroblasts." (PMID 18373849, 2008). "We noted that some of the Mmp13 mRNA positive myofibroblasts were located in narrow bands between tumor cell clusters." (PMID 18698413, 2008). "One hundred and eleven out of 127 specimens with high levels of tumor expression of MMP-13 (87.40%) featured high levels of MMP-13 in peritumoral fibroblasts." (PMID 18373849, 2008). "The increase in Mmp13 mRNA thus took place during the time of transition to invasive stages in this tumor model." (PMID 18698413, 2008). "This focal expression of Mmp13 in the tumor core was very different from the expression of Mmp2 and Mmp14, which were found throughout the tumor stroma, including at the tumor periphery, and in areas with hyperplasia, grade I and grade II MIN (not shown)." (PMID 18698413, 2008). "It is therefore likely that MMP13 resides in the tumour microenvironment in both early and advanced cancer stages, resulting in low to very low levels entering the circulation." (PMID 18366705, 2008). "Mmp13 mRNA was induced in tumors from mice of 7–9 weeks-of-age, and we therefore expected that MMP13 would be required in the later stages of tumorigenesis, possibly affecting tumor growth and metastasis." (PMID 18698413, 2008). "Consistently, 106 out of 144 specimens with low levels of tumor expression of MMP-13 were accompanied by peritumoral fibroblasts that expressed MMP-13 at low levels." (PMID 18373849, 2008). "In particular, Mmp13 mRNA positive cells were often seen in stromal branches located close to the tumor cores with focal necrosis." (PMID 18698413, 2008). "Cross species comparative analysis with aCGH data of human cancer cell lines revealed known and candidate oncogenes (Mmp13, Slamf6, and Rreb1) and tumor suppressors (Wwox and Arfrp2)." (PMID 18485879, 2008). "MMP-13 expression by tumor cells (p < 0.001) and stromal fibroblasts (p <0.001) both correlated with carcinoma infiltration of lymph nodes." (PMID 18373849, 2008). "The positive immunohistochemical reactivity to MMP-13 appeared as brown cytoplasmic and nuclear staining reaction was also identified in tumor cells." (PMID 18554405, 2008). "While several studies conclude that MMP-13 is produced by tumor stromal fibroblast-like cells, others claim that MMP-13 is synthesized predominantly by tumor cells." (PMID 18373849, 2008). "Overall, the detection of cytoplasmic MMP-13 in tumor cells, correlated significantly with the cytoplasmic MMP-3 in the peritumoral fibroblasts (p < 0.0001)." (PMID 18373849, 2008). "In this sense, overexpression of collagenase-1 (MMP1) and collagenase-3 (MMP13) has been associated with more aggressive tumors and poor prognosis in different tumor types." (PMID 19094243, 2008). "Archival tumor tissues from 11 patients with chondrosarcoma of the jaws were analyzed by immunohistochemistry for the expression of MMP-13." (PMID 18554405, 2008). "Using quantitative RT–PCR, overexpression of MMP1, MMP3, MMP7, MMP11, MMP12 and MMP13 in desmoid tumours was demonstrated." (PMID 15054469, 2004). "Although expression of cytoplasmic MMP-13 was primarily detected in tumor cells, it also was seen in stromal cells." (PMID 15291964, 2004). "Elevated MMP-13 expression has been found in a number of different malignancies, and expression has been related to tumor behavior and patient prognosis." (PMID 15291964, 2004). "Others have reported that MMP-13 is not only expressed by tumor cells in the invading periphery of most SCCs but also by stromal cells in a subset of tumors." (PMID 15291964, 2004).
tumor (continued). "MMP13 contributes to extracellular matrix degradation and tumor invasion." (PMID 41529246, 2026). "MMP13 is also positively correlated with CD8+T infiltration, which specifically identifies tumour-associated antigenic peptides presented on cell surfaces and mediates cytotoxic effects through the release of IFN-γ, granzyme B, and perforin, ultimately inducing tumour cell lysis." (PMID 40243781, 2025). "The mechanical stretching TGF-β signalling pathway in normal myoepithelial cells induces a ductal carcinoma in situ (DCIS) phenotype associated with integrin-β6 expression, thereby affecting the expression of proteases such as MMP13 and promoting the invasion behaviour of tumour cells." (PMID 40243781, 2025). "Targeting the spatiotemporal regulation of MMP13’s mechanobiological functions may offer novel therapeutic strategies for disrupting the tumour–stroma vicious cycle." (PMID 40243781, 2025). "In addition, MMP-13-mediated proteolysis of laminin-5 has been shown to enhance tumor invasiveness, though it concurrently disrupts vasculogenic mimicry." (PMID 41471689, 2025). "Thus, while MMP13 and M1 TAMs can have anti-fibrotic and tumour-suppressive effects, their roles in the TME are complex and context-dependent." (PMID 40243781, 2025). "MMP13-mediated stromal degradation creates a different microenvironment for tumour development." (PMID 40243781, 2025). "To further explore the molecular mechanisms underlying these observations, we examined the expression of key extracellular matrix (ECM)-degrading enzymes, matrix metalloproteinase (MMPs), particularly MMP9 and MMP13, which are crucial mediators of tumor invasion and metastasis." (PMID 40332124, 2025). "Inhibition of MMP-13 may contribute to the inhibition of tumor progression, including processes such as invasion, angiogenesis, and metastasis." (PMID 41471689, 2025). "Therefore, remote tumor-derived sEVs carrying HTRA1 strongly upregulated MMP-13 in OPs, significantly disrupting the bone marrow ecosystem." (PMID 40103824, 2025). "Mmp13 gene downregulation in the Myd88KO tumor group could be attributed to the fact that the MMP13 protumor activity may be mediated through the MyD88/ERK/NF-κB signaling pathway." (PMID 39000291, 2024). "Fibroblasts and tumor cells can secrete MMP-13, MMP-7, and MMP-14." (PMID 39247608, 2024). "Also, other genes associated with metastasis and cancer progression were differentially regulated in tumour tissue, i.e., MMP13, WNT5B, and SOSTDC1." (PMID 39202425, 2024). "Finally, HtrA serine peptidase 1 (HTRA1) on tumor-derived vesicles has been reported to upregulate MMP13 in osteoprogenitors which subsequently induce CD41- GMP clustering and systemic accumulation of protumoral Neu." (PMID 39148724, 2024). "In addition, the AUC of EFNA1 and MMP13 for diagnosing GC were 0.723 and 0.761, respectively, while the AUC of GC using both two tumor markers was 0.794." (PMID 38987376, 2024). "Fibroblasts and tumour cells secrete MMP-13, MMP-7, and MMP-14." (PMID 38911387, 2024). "MMP13 levels were associated with loss of ECM integrity, which may lead to increased T cell infiltration as well as tumor invasion." (PMID 38774209, 2024). "Specifically, LIF and GM-CSF secretion was PKD-dependent in the metastatic cell lines MDA-MB-231, MDA-MB-468 and MDA-MB-436, compared to one primary tumor cell line while the secretion of IL-11 and MMP-13 was found to be regulated by PKD only in metastatic TNBC cells." (PMID 38323010, 2024). "Moreover, EFNA1 combined with MMP13 potentially demonstrated a better diagnostic sensitivity for early-stage GC patients than markers CEA and CA19-9, which are major serum tumor markers in gastrointestinal cancers currently used in clinical practice." (PMID 38987376, 2024). "Additionally, LINC00511 can also promote tumor cell proliferation by alleviating the inhibitory effect of miR-150 on matrix metalloproteinase 13 (MMP13)." (PMID 39206156, 2024).
tumor (continued). "Furthermore, the GOLM1 gene, encoding a resident cis-Golgi membrane protein, promote epithelial–mesenchymal transition (EMT) and tumor cell proliferation, activating matrix metalloproteinase-13 (MMP13) signaling events that contribute to NSCLC aggressiveness." (PMID 39766023, 2024). "MMP13 is also a key factor in tumor tissue invasiveness, metastasis, and prognosis." (PMID 38987376, 2024). "MMP13, CEMIP, and DESC1 encode proteins important for degradation of extracellular matrixes, expressed in the tumor invasion front, and are reported to increase cell migration and tumor cell extravasation." (PMID 39468006, 2024). "Furthermore, Vitex induced antimetastatic activity by suppressing the migration and invasion of MMP13, which is the primary protease that degrades type I collagen for tumour-induced osteolysis in bone tissues and preferential metastasis sites." (PMID 38612399, 2024). "Proteins associated with tumor progression or a bad prognosis such as WNT5A, MMP13, MMP3, telomerase, and NOTCH3 were upregulated while proteins associated with immune cell infiltration or pathway inhibitors/tumor suppressors such as FRZB, CD177, PPARG, and HRASLS2 were downregulated." (PMID 38504345, 2024). "In addition, metalloproteinases MMP3, MMP9, MMP10 and MMP13, known to promote tumor growth, were upregulated by CX3CL1 mediated activation of CX3CR1." (PMID 37771579, 2023). "Moreover, a number of studies indicate that downregulation of MMP‐13 is correlated with tumour metastatic suppression." (PMID 37710409, 2023). "The efficacy of MMP carborane 4 may depend on tumor types as shown in our data, MMP-13 expression may vary among tumor types and should be noted." (PMID 37108137, 2023). "Additionally, immune correlation analysis showed that MMP13 expression was significantly associated with TMB, MSI, and tumor immune infiltration." (PMID 37000142, 2023). "Furthermore, immunohistochemistry (IHC) demonstrated that BF-TK/GCV reduced the expression of HIF−1α, mTOR, NF-κB1-p105, VCAM1, MMP13, CXCL12, ATG16, and CEBPB, which were associated with tumor metastasis." (PMID 37511481, 2023). "MMP-13′s enzymatic activity reshapes the tumour microenvironment, favouring tumour advancement." (PMID 38067138, 2023). "MMP13 can also digest the dense extracellular collagenous matrix surrounding tumors, so as to increase the sensitivity of tumors to chemotherapy and enhance anti-tumor activity." (PMID 37609436, 2023). "Consequently, MMP-1 and MMP-13 synthesis and laminin-332 accumulation are inhibited leading to attenuated cell invasion and tumor growth." (PMID 37864034, 2023). "Specifically, MMP9, MMP13, MMP11, and CEMIP were positively associated with the tumor immune microenvironment, while SLPI, SLC2A1, SERPINB5, HK2, CEACAM6, and CEACAM5 were negatively associated with the tumor immune microenvironment." (PMID 37234801, 2023). "Previously, MMP-1 and MMP-13 have been shown to be specifically expressed by tumor cells in cSCC." (PMID 36010973, 2022). "Importantly, the treatment of 5TGM1 MM mice with an MMP13 inhibitor reduced the serum glycine concentration and inhibited tumor progression." (PMID 35817773, 2022). "It was also reported that the DRD2 agonists could exert anti-tumor effects through ROCK-mediated inactivation of Cofilin-1 or inhibiting EGFR/AKT/MMP-13 pathway." (PMID 35463319, 2022). "MMP-13 occurs in primary tumour cell-derived exosomes under hypoxic conditions." (PMID 35805035, 2022). "Given its powerful and destructive action toward ECM, it is not surprising that expression of MMP-13 in tumor creates a more favorable environment for tumor growth, whilst its overexpression is often associated with tumor aggressiveness and poor prognosis." (PMID 36713871, 2022). "This shows that MMP13 produced by tumor cells activates osteoclasts and promotes bone metastasis." (PMID 35281094, 2022).
tumor (continued). "However, MMP-13 seems to play multiple roles in tumor progression and metastasis since its expression is enhanced in various cancers." (PMID 36713871, 2022). "CTHRC1 with POSTN and MMP13 could potentially affect ECM remodelling which in turn could aid in tumor cell migration and invasion." (PMID 36190948, 2022). "For example, MMP-13 promotes tumour angiogenesis and leads to tumour invasiveness." (PMID 36555218, 2022). "About 65% of eyelid BCCs, as discovered by another study, had MMP-13 up-regulation in the epithelial tumoral cells located at the leading edge, which may explain the aggressive nature of this tumor." (PMID 36505148, 2022). "Overexpression of COX-2 and MMP-13 has been reported in many clinical GC specimens and may be related to tumor invasion, metastasis, tumor-node-metastasis stage, and overall survival of patients with GC." (PMID 34729107, 2021). "MMP2, MMP9 and MMP13 are prominent enzymes that promote tumor cell invasion and migration and regulate the progress of epithelial-to-mesenchymal transition (EMT), which is a transformation process of the epithelial cells to the mesenchymal cells and can promote cancer metastasis." (PMID 34820358, 2021). "Tumor tissues had a remarkably higher level of MMP-13 than control tissues." (PMID 34266392, 2021). "MMP-13, also termed collagenase-3 responsible for cleavage of fibrillar collagens, gelatin and fibronectin, is not detectable in intact normal skin, but its expression has been shown in tumor tissues from patients with cSCC and SCC of the head and neck." (PMID 34266392, 2021). "Moreover, an abnormal matrix is formed in tumour tissue when MMP13 and other matrix metalloproteinase activity is too high, and this leads to greater invasion, metastasis and worse prognosis." (PMID 33807045, 2021). "In contrast, MMP-9 and MMP-13 were expressed mainly in the healthy skin adjacent to the tumor." (PMID 34204372, 2021). "SOX9 may also act as a putative proto-oncogene, influencing tumor malignancy and aggressiveness, possibly via the activation of MMP13." (PMID 33076370, 2020). "The relevance of increased MMP expression is not well documented and only a single study showed that MMP-13 expression is associated with lymph node metastasis and the tumor’s pathological stage." (PMID 32325664, 2020). "Therefore, miR-125b plays a tumor suppressor role, targeting both MMP13 and STAT3 mRNAs with inhibition of cell proliferation and migration, and induction of cell apoptosis." (PMID 32911687, 2020). "Whilst the molecular basis for this requires further experimentation it is interesting that MMP1 and MMP13 have been found to be upregulated in a variety of different tumours, including cervical, whilst MMP8 on the other hand has been associated with an anti-invasive effect in certain settings." (PMID 31116803, 2019). "MMP-13 is shown to be overexpressed in varieties of tumors, which implies that a high level of MMP-13 may be closely related to tumor invasion, metastasis, and poor prognosis in several forms of cancer." (PMID 30889876, 2019). "MMP-13 knockdown reversed the promotion of tumor growth by hypoxic exosomes." (PMID 29515112, 2018). "Tumor-derived exosomes could function as a messenger that delivers MMP-13 between normoxic and hypoxic cancer cells and thus remodels the tumor microenvironment of NPC." (PMID 29515112, 2018). "Furthermore, we provide evidence that the silencing of MMP13 inhibits ETV4-induced tumor formation in mice, confirming the in vitro data and highlighting the importance of MMP13 activity in ETV4 tumorigenic functions." (PMID 29996935, 2018). "Thus, MMP13 acts as a relay of ETV4 in its functional role in the mammary epithelial tumorigenic cells in vitro as well as in tumor development in animal models." (PMID 29996935, 2018). "This suggests that MMP‐13 may play a major role in regulating tumour blood supply in the late stages of tumour growth." (PMID 28766880, 2017).
tumor (continued). "The expression levels of ADARB1 (P<0.01), ADRB2 (P<0.05) and ANKRD1 (P<0.05) were significantly down-regulated in stage I LUAD tissues; COL1A1 (P<0.05) and MMP13 (P<0.05) were significantly up-regulated in stage I LUAD tissues compared with adjacent non-tumor tissues." (PMID 28881680, 2017). "The expression levels of MMP‐13 showed a gradually increasing trend with tumour growth." (PMID 28766880, 2017). "MMP‐13 plays an important role in the matrix degradation process, which has been confirmed to promote tumour invasion, migration and angiogenesis in a variety of tumours 23, 24, and thus, we initially believed it could promote the formation of VM." (PMID 28766880, 2017). "The results confirmed the relationship between MMP‐13 expression and VM and EDVs, and a correlation analysis showed that MMP‐13 expression was negatively correlated with the number of VM networks in tumour cells but positively correlated with the number of EDVs." (PMID 28766880, 2017). "Additionally, we found that the downstream target genes just like ZEB1 and MMP13, which play an important role in tumour regulation, were decreased in the INTS6 overexpressing cells." (PMID 28899352, 2017). "Furthermore, MMP-13 is involved in the maintenance of angiogenesis through the release of VEGF from the tumor ECM." (PMID 27271600, 2016). "Subsequent examination using 143B cells revealed that knockdown of PAI‐1 expression resulted in downregulation of the expression and secretion of matrix metalloproteinase‐13 (MMP‐13), which is also a target gene of miR‐143 and a proteolytic enzyme that regulates tumor‐induced osteolysis." (PMID 26817521, 2016). "However, although at lower transcriptional levels, MMP3 and 19 were significantly upregulated whereas MMP13 were significantly downregulated in the SG-/- primary tumour tissue." (PMID 27223472, 2016). "In this way, MMP-13 is implicated both in metastatic and non-metastatic tumors, where molecular expression is spurred by numerous cytokines, growth factors and tumor promoters that act on tumor cells." (PMID 27765913, 2016). "Moreover, MMP-10 up-regulates several other MMPs such as MMP-1, MMP-7, MMP-9, and MMP-13 that are essential for tumor progression." (PMID 27271600, 2016). "MMP-13 has great substrate specificity and is a powerful tool for tumor invasion." (PMID 27271600, 2016). "Immunoreactivity to MMP-13 was identified in 91% and localized to tumor cells." (PMID 27716617, 2016). "The expression of MMP-13 has been associated with the presence of tumor cells in the bone marrow of non-small lung cancer patients, and a reduced prognosis compared to MMP-13 negative patients." (PMID 25664615, 2015). "We showed a decrease in metastatic tumor burden in Mmp13−/− mice compared to wildtype mice, explained in part by a reduction in the number of tumor cells extravasating from the hepatic vasculature in the Mmp13−/− mice compared to wildtype mice." (PMID 25880591, 2015). "Elevation of MMP13 in the steatotic liver suggested that it could play an important role in priming the steatotic liver microenvironment for tumor establishment." (PMID 25880591, 2015). "Data from other investigators suggest that expression of MMP-13 may serve as a biomarker of poor prognosis in NSCLC patients, associated with bone marrow microinvolvement by tumor cells." (PMID 26193700, 2015). "MMP13 can cleave, release and activate cytokines thereby altering recruitment and or activation of inflammatory cells such as neutrophils and macrophages that have been shown to facilitate tumor cell extravasation." (PMID 25880591, 2015). "Likewise, the MMP-13 staining index of EGFR mutated (n = 3) and EGFR wild-type (n = 22) tumors was comparable for both in tumor cells and fibroblasts (p = 1 for tumor cells and p = 0.23 for fibroblasts; Fisher’s exact test)." (PMID 26193700, 2015). "We found that MMP-13 cleaves laminin-5 (Ln-5) into small fragments to accelerate tumor metastasis." (PMID 25749207, 2015).